RNU6-22P (RNA, U6 small nuclear 22, pseudogene)
Synonyms: RNU6-22
Gene: Small nuclear RNA gene on chromosome 16 (69,175,671 to 69,175,777, reverse strand). Ensembl gene ENSG00000207083.
Homologues: Orthologues: rat LOC120101151 (96% identical), pig U6 (95% identical), rat U6 (95% identical), dog U6 (93% identical), pig U6 (92% identical). Paralogues in human: RNU6-17P (97% identical), RNU6-18P (97% identical), RNU6-33P (97% identical), RNU6-1 (96% identical), RNU6-12P (96% identical), RNU6-13P (96% identical), RNU6-2 (96% identical), RNU6-32P (96% identical), RNU6-3P (96% identical), RNU6-4P (96% identical), RNU6-5P (96% identical), RNU6-6P (96% identical), and 1285 more.